CD14 (CD14 molecule)
Diseases named in the same sentence as CD14 in open-access papers (continued):
Sharing a sentence is not in itself a finding about the gene and the disease.
Sepsis (continued). "This meta-analysis demonstrated that CD14-159C/T polymorphism is likely to be associated with susceptibility to sepsis in Asian population, especially for the TT genotype." (PMID 28122493, 2017). "On the other hand, the study evaluated the associations between CD14 polymorphism and sepsis-related mortality." (PMID 28122493, 2017). "The association between CD14-159C/T polymorphism and sepsis has been assessed but results of current studies appeared conflicting and inconstant." (PMID 28122493, 2017). "The importance of CD14 in inflammatory processes is underscored by its association with a multitude of diseases, including sepsis, cardiovascular disease, periodontitis, tuberculosis and atopic asthma." (PMID 28302109, 2017). "A mass of studies reported the associations between CD14 SNP and incidence of sepsis, or sepsis-related mortality." (PMID 28122493, 2017). "The association between the CD14-159C/T polymorphism and susceptibility to sepsis was analyzed in these independent studies with 788 cases and 730 controls." (PMID 28122493, 2017). "CD14-159C/T (rs2569190) is a functional polymorphism located in the 5′UTR of the promoter region of CD14 gene, counting from the transcription start site, with a potential role of decreasing or increasing gene expression in process of sepsis." (PMID 28122493, 2017). "In conclusion, the present study revealed a potential association between CD14-159C/T polymorphism and susceptibility to sepsis in the Asian population, especially the CD14-159 TT genotype." (PMID 28122493, 2017). "Establishment of a definite association between sepsis and CD14 polymorphisms requires further trials with larger patient numbers and optimized methodology." (PMID 28122493, 2017). "As our study revealed, CD14 polymorphism was proved irrelevant to sepsis-related mortality in total population." (PMID 28122493, 2017). "Compared with the C-allele carrier of CD14 rs2569190, TT-homozygous patients had a favorable outcome in sepsis." (PMID 28149700, 2017). "Malnutrition, high plasma endotoxin and sCD14 levels, single TLR4+896A/G or CD14-159C/T variant allele carriers and double variant allele carriers are significant predictive factors for the development of severe sepsis among them." (PMID 27861595, 2016). "The phagocytic abilities of CD16- monocyte were significantly decreased among cases carrying variant TLR4+896A/G or CD14-159C/T allele and severe sepsis." (PMID 27861595, 2016). "Further analysis indicated that there was a positive correlation between LPS-stimulated mCD14 densities and phagocytic index on CD16- monocyte in CD14-159C/T variant allele carriers with severe sepsis." (PMID 27861595, 2016). "Nonetheless, above mention phenomena was disappeared among CD16- monocytes collected from cases carrying variant TLR4+896A/G or CD14-159C/T allele and severe sepsis." (PMID 27861595, 2016). "Accordingly, it was reasonable to observe a significant negative correlation between plasma endotoxin levels and LPS-stimulated CD16- (classical) monocyte HLA-DR expression in our TLR4+896A/G or CD14-159C/T variant allele carriers with severe sepsis." (PMID 27861595, 2016). "More recently, the soluble CD14 subtype, Presepsin, appears to be an accurate sepsis diagnostic marker and rises up a great clinical interest." (PMID 27389015, 2016). "For CD14-159C/T variant allele carriers with severe sepsis, persist endotoxemia inhibited mCD14/HLA-DR expression and impaired phagocytosis of their classical monocyte." (PMID 27861595, 2016). "Further, low mCD14 density on CD16- (phagocytic) monocytes contributed to increased severe sepsis risk in CD14-159C/T variant allele carriers." (PMID 27861595, 2016). "The soluble CD14 subtype, Presepsin, appears to be an accurate sepsis diagnostic marker, but data from intensive care units (ICUs) are scarce." (PMID 27389015, 2016).
Sepsis (continued). "Among all cases, 59% of TLR4+896A/G variant allele carriers complicated with severe sepsis whereas 43% of CD14-159C/T variant allele carriers complicated with severe sepsis." (PMID 27861595, 2016). "Significantly, increased proportion of CD16+ monocyte subsets were observed in TLR4+896A/G or CD14-159C/T variant allele carriers and severe sepsis cases." (PMID 27861595, 2016). "We sought to detect the effect of global genetic ablation of TLR4 or CD14 (TLR4−/−, CD14−/−) in a clinically relevant model of polymicrobial sepsis caused by CLP in mice." (PMID 27349568, 2016). "Both on the CD16- and CD16+ monocyte, the significantly lower baseline and LPS-stimulated HLA-DR expression were observed in cases carrying variant TLR4+896A/G or CD14-159C/T allele carriers and severe sepsis." (PMID 27861595, 2016). "Accordingly, higher percentage (69%) of double TLR+896A/G and CD14-159C/T variant allele carriers were complicated with severe sepsis compared to either single TLR+896A/G or CD14-159C/T variant alleles carriers (59% or43%)." (PMID 27861595, 2016). "In univariate analysis, the odd ratio for predicting severe sepsis among TLR4+896A/G variant allele carriers was 2.41 whereas 1.82 for CD14-159C/T variant allele carriers." (PMID 27861595, 2016). "In conclusion, this is the first study to show a beneficial association of the CD14 rs2569190 TT genotype with short-term survival (30-day) in a cohort of sepsis patients of exclusively western European descent." (PMID 26020644, 2015). "According to our observations, it is worthwhile to consider CD14 rs2569190 genetic variants in future studies that investigate the genetic risk stratification for short-term mortality in patients with sepsis." (PMID 26020644, 2015). "The rs11536889 polymorphism in TLR4 and rs2563298 polymorphism in CD14, and two haplotypes were associated with increased susceptibility to sepsis." (PMID 25394369, 2014). "This study is the first to assess the potential implications of CD14 gene rs2563298 on susceptibility to sepsis." (PMID 25394369, 2014). "We found that the severity of sepsis was mainly associated with CD14 rs2569190-GG and to IL8 rs4073-AT." (PMID 25000179, 2014). "One meta-analysis evaluated the associated between CD14 promoter -159C/T polymorphism and the risk of sepsis." (PMID 25394369, 2014). "The rs11536889 polymorphism in TLR4 and rs2563298 polymorphism in CD14 were significantly associated with the risk of sepsis when compared to the control group." (PMID 25394369, 2014). "In summary, this study indicates that SNPs (TLR4: rs 11536889 and CD14: rs2563298) and two haplotypes are associated with susceptibility to sepsis in a Chinese population." (PMID 25394369, 2014). "Increased membrane-bound or soluble CD14 levels are well-established biological risk factors for the development of sepsis and subsequent vital organ dysfunction both in animal experiments and in critically ill patients." (PMID 23990939, 2013). "We summarized the data on the association between CD14-159C/T polymorphism and sepsis in the overall population and subgroup by ethnicity and sepsis subtype." (PMID 23990939, 2013). "We found that the way in which sepsis was described affected the association between CD14-159C/T and susceptibility to sepsis." (PMID 23990939, 2013). "In the present study, we identified 17 genetic association studies and used meta-analysis to evaluate the association of CD14-159C/T polymorphism with sepsis under the dominant, recessive and allelic genetic model respectively." (PMID 23990939, 2013). "There were modest heterogeneities in the overall comparisons for CD14-159C/T polymorphism and sepsis risk." (PMID 23990939, 2013). "We noted that the effect of CD14-159C/T on sepsis risk was more pronounced in Asians under the dominant genetic model (OR = 1.38, 95%CI = 0.96–1.98, P = 0.08), although there was only borderline significant difference." (PMID 23990939, 2013).
Sepsis (continued). "Nonetheless, to the best of our knowledge, the present study represents the first meta-analysis investigating the relationship between CD14 gene C-159T polymorphism and risk of sepsis." (PMID 23990939, 2013). "In at least one well-controlled study,34ethnicity played a major role in modifying associations between polymorphisms in immunologically relevant genes (IL-6 and CD14) and sepsis-related outcomes." (PMID 24310803, 2013). "The experiments of this study demonstrated that TLR4-deficiency protected partly and TLR9- as well as CD14-deficiency protected completely from sepsis-induced vasoplegia." (PMID 22970242, 2012). "In patients with sepsis, death was associated with significant lower CD14 and TLR2 expression at admission (CD14: 25.7 +- 19.1 vs 39.1 +- 17.3 mean fluorescence intensity [MFI], p = 0.02; TLR2: 21.8 +- 9.4 vs. 30.9 +- 9.6, p = 0.01)." (PMID 19371402, 2009). "The purpose of this study was to determine if there is a relationship between the IL-10 -1082 G/A, IL-6 -174 G/C and CD14 -260 C/T SNPs and risk for or outcome from sepsis in mechanically ventilated very low birth weight (VLBW) infants." (PMID 16611358, 2006). "Therefore, this evidence indicates a role for myeloid cells (IL1B+ macrophages or CD14+ monocytes) as a shared cellular associated with the progression of Sepsis and IBD." (PMID 39993996, 2025). "A subset of CD14+ monocytes (M5) expressing CD86lo, a protein downregulated with LPS stimulation and sepsis, was associated with NIH activity index and fibrinoid necrosis among patients without immunosuppression and with prednisone ≤ 5 mg, suggesting an inflammatory state." (PMID 40536813, 2025). "In addition, CD14 has been implicated in the pathogenesis of autoimmune diseases and associated with the host response to sepsis." (PMID 39767701, 2024). "Low expression of ARHGEF10L in CD14 + monocytes is associated with increased death from sepsis, and the list included genes related to anti-bacterial activity (LCN2), regulation of TLR4 responses (SLC15A3), LPS sensitivity and autophagy (RUBCNL and SLC8A1) and apoptosis (FAS, TNFRSF21, TNFRSF8)." (PMID 39730996, 2024). "Our MR study demonstrated a significant association between the immunophenotype and the susceptibility, severity, and mortality of patients with sepsis, providing, for the first time, substantial evidence of the role of CD14+ CD16+ monocytes in the potential sepsis-related risks." (PMID 39076981, 2024). "For this reason, we investigated whether LPA3 deficiency affected the level of CD14 on the surface of monocytes in mice with sepsis." (PMID 35464399, 2022). "Impaired monocyte phagocytic activity and defective TLR4 expression in the CD14+highCD16− and CD14+highCD16+ monocyte subsets might be involved in common causes, predominantly septicemia, of death in the years following SCI." (PMID 33451043, 2021). "In our study, however, we could demonstrate that sepsis-associated increases in CTCF binding remain observable within 7 days within the MHC-II region of blood-derived CD14+ monocytes." (PMID 33939725, 2021). "Likewise, we found that P2X7 receptor deficiency or its pharmacological inhibition reduces CD14 in peritoneal lavage and serum when mice are subjected to a sepsis model." (PMID 33135636, 2020). "To test if the deficiency in extracellular CD14 in P2rx7−/− mice during sepsis would be detrimental for survival, we treated P2rx7−/− mice with recombinant CD14 before CLP and found that mice survival was significantly increased, as well as weight loss was preserved." (PMID 33135636, 2020). "Several studies tried to establish an association between CD14 polymorphism and sepsis." (PMID 28122493, 2017). "This analysis was aimed to determine whether the CD14-159C/T polymorphism confers susceptibility to sepsis or is associated with increased risk of death from sepsis." (PMID 28122493, 2017).
Sepsis (continued). "Our purpose in the current work is to determine whether this variant in CD14 is associated with an increased risk of sepsis or higher sepsis-related mortality by means of a human genome epidemiology review including a meta-analysis of previous data." (PMID 28122493, 2017). "Thus, in the present study, we identified 15 genetic association studies and used meta-analysis with the genetic model to evaluate the association of CD14-159C/T polymorphism with sepsis." (PMID 28122493, 2017). "As is witnessed by the recent decades, an explosion of research occurred to address the effect of genetic predisposition on the development and course of sepsis, and a single nucleotide polymorphism (SNP) in CD14 with a frequency higher than 1% in the population succeeded to draw global attention." (PMID 28122493, 2017). "Notably, the magnitude of LPS-stimulated HLA-DR expression determined the phagocytosis of CD16- monocyte in TLR4+896A/G and CD14-159C/T variant allele carriers with severe sepsis." (PMID 27861595, 2016). "Additionally, the mCD14 density was remarkably decreased on CD16- monocyte of CD14-159C/T variant allele carriers and severe sepsis cases." (PMID 27861595, 2016). "Biomarkers like Soluble CD14 subtype (sCD14-ST, presepsin) may be useful in identifying patients with sepsis and its diagnostic superiority has been confirmed by several preliminary studies." (PMID 26642970, 2015). "A functional polymorphism within the CD14 gene, rs2569190, has been shown to impact the pro-inflammatory response upon stimulation with lipopolysaccharide, a central mediator of inflammation in sepsis." (PMID 26020644, 2015). "Recently, the -260C/T polymorphism in CD14 gene has been investigated the association with many diseases, such as inflammatory bowel disease, alcoholic liver disease, tuberculosis, sepsis, coronary heart disease, asthma and allergic rhinitis." (PMID 24978812, 2014). "This study was designed to evaluate whether the TLR4 and cluster CD14 gene polymorphisms are associated with susceptibility to sepsis." (PMID 25394369, 2014). "Several studies have shown that polymorphisms in TLR4 and CD14 genes may relate to the susceptibility with some infection induced diseases, e.g. sepsis, but this is controversial." (PMID 25394369, 2014). "Accordingly, we conducted a comprehensive literature search and a meta-analysis to determine whether the CD14-159C/T polymorphism conferred susceptibility to sepsis or was associated with increased risk of death from sepsis." (PMID 23990939, 2013). "We set to analyze published data and hope to provide more power and precise estimation of the clinical impact of CD14-159C/T polymorphism, to determine whether CD14-159C/T is associated with the risk of sepsis or sepsis-related mortality by a meta-analysis." (PMID 23990939, 2013). "Moreover, there was borderline association between CD14-159C/T and sepsis mortality under the dominant genetic model (OR = 1.44, 95%CI = 0.98–2.11, P = 0.06)." (PMID 23990939, 2013). "Therefore, candidacy of CD14 for sepsis is well-suggested and its C-159T polymorphism has been reported to be associated with sepsis by some studies." (PMID 23990939, 2013). "Presepsin, generated by circulating plasma proteases activating cleavage of soluble CD14, is a novel biomarker that has been used for diagnosis of sepsis in recent years, and its production is associated with phagocytosis and cleavage of microorganisms by lysosomal enzymes." (PMID 24138799, 2013). "Data indicate that SNPs of TNF-α, Il-1β, PAI-1, and CD14 may be associated with a poor prognosis from sepsis." (PMID 17877801, 2007). "A soluble peptide, namely, CD14 subtype (sCD14-ST) or presepsin, was demonstrated to have a close relationship with monocyte dysfunction, and its circulating level was applied as a candidate for early diagnosis and risk stratification in patients with sepsis and septic shock." (PMID 35619710, 2022).
Sepsis (continued). "In addition, other specific studies have associated CD14 rs2569190 G allele with higher risk of sepsis and death in people of European origin, which may support our results." (PMID 29426837, 2018). "However, subgroup meta-analyses indicated significant association between the CD14-159C/T polymorphism and susceptibility to sepsis in additive model and recessive model (CC versus TT: OR = 0.53, 95% CI 0.29–0.95, p = 0.03; CC versus CT + TT: OR = 0.50, 95% CI 0.30–0.85, p = 0.010)." (PMID 28122493, 2017). "Notably, in our febrile acute de-compensated cirrhotic patients with severe sepsis, low mD14 expression is characterized by the decreased LPS-stimulated phagocytic ability of classical monocyte, whereas high plasma sCD14 level indicated uncontrolled sepsis among CD14-159C/T variant allele carriers." (PMID 27861595, 2016). "However, above correlation was loss among variant CD14-159C/T allele carriers with severe sepsis." (PMID 27861595, 2016). "Genotyping analysis of eight SNPs in TLR4 and CD14 genes were performed by using Snapshot SNP genotyping assays and DNA sequencing methods to investigate whether the gene polymorphisms are associated with susceptibility to sepsis." (PMID 25394369, 2014). "Candidate genes were identified through overlap of differentially expressed genes between CD14-high and CD14-low samples and sepsis-related WGCNA modules." (PMID 42291298, 2026). "The last observed soluble receptor was CD14, which is also known as “presepsin,” and its serum detection is used as a marker of sepsis and systemic inflammatory response syndrome in newborns." (PMID 41474380, 2026). "Subsequently, we measured the mRNA expression of SLC25A22, SLC25A33, and SLC25A37, along with that of pro-inflammatory cytokines, including TNF-α, IL-6, and IL-1β, in CD14+ monocytes from sepsis patients with liver abscesses." (PMID 40384854, 2025). "Our findings indicate that an MFI of CD38 ≥ 14 382 in CD14+ monocytes can serve as a threshold to define CD38high monocytes, effectively differentiating sepsis from non‐infectious inflammation." (PMID 40145840, 2025). "In patients with severe sepsis and septic shock, the proportion of CD14+CD16+ monocytes was significantly elevated." (PMID 41246299, 2025). "SLC25A33 expression was significantly elevated in CD14+ monocytes derived from patients with sepsis and LPS/interferon-gamma (IFN-γ)-stimulated peritoneal macrophages (PMs)." (PMID 40384854, 2025). "We investigated possible IL1B+macrophages and CD14+ monocyte pathways since systemic IBD and Sepsis are associated with enhanced cell ratios and pronounced hub gene expression." (PMID 39993996, 2025). "Presepsin, a soluble fragment of CD14 released during phagocytic activation, has emerged as a promising biomarker for early sepsis detection." (PMID 40804836, 2025). "TLR4 also interacts with CD14, damage-associated molecular patterns (e.g., HMGB1), and NETs, amplifying inflammatory and coagulation pathways that link thrombocytopenia and sepsis progression." (PMID 40003683, 2025). "Drugs targeting CD14 have been applied in the treatment of sepsis with atibuclimab and autoimmune diseases, such as psoriasis and ulcerative colitis with the example of VB-201." (PMID 41049426, 2025). "In a study by Guanguan Qiu and colleagues, CD14++CD16+ (CD16+) monocytes were positively correlated with severe sepsis and early disease severity scores in infectious shock." (PMID 40124361, 2025). "Regarding innate immunity, the number of circulating monocytes (CD14+ monocytes) is increased in patients with Sepsis, and the monocytic distribution width has emerged as a promising biomarker for Sepsis." (PMID 39993996, 2025). "Our findings suggest that genetically determined increases in certain immune cell phenotypes, such as CCR2 on CD14 − CD16 + monocytes, HLA-DR + natural killer absolute count, and CD3 − lymphocyte %leukocyte, are associated with a reduced risk of sepsis." (PMID 40797460, 2025).